LATS1 (large tumor suppressor kinase 1)
Diseases named in the same sentence as LATS1 in open-access papers (continued):
Sharing a sentence is not in itself a finding about the gene and the disease.
glioma (continued). "The results showed that the level of LATS1 expression was an independent prognostic factor for glioma (P<0.001)." (PMID 22909338, 2012). "We demonstrated the functional importance of LATS1 in suppressing glioma cell growth, migration, invasion and cell cycle transition from G2 to M phase." (PMID 22909338, 2012). "The relationships between clinicopathologic features and LATS1 expression levels in individuals with glioma were analyzed." (PMID 22909338, 2012). "In order to assess the role of LATS1 in glioma, we first performed real-time PCR to measure the expression of LATS1 mRNA transcripts in 17 paired glioma samples and their adjacent brain tissues." (PMID 22909338, 2012). "In the present study, we examined the expression of LATS1 in gliomas and explored its role as a tumor-suppressor gene in glioma cells in vitro." (PMID 22909338, 2012). "In order to assess the role of LATS1 in glioma, we performed real-time PCR to measure the expression of LATS1 mRNA transcripts in 17 paired gliomas and their adjacent brain tissues." (PMID 22909338, 2012). "In exploring the molecular mechanism of LATS1 tumor-suppressing function in glioma, we found that restoration of LATS1 expression significantly inhibited expression of cell cycle factor CCNA1 in glioma U251 cells." (PMID 22909338, 2012). "Further, we presented the evidence that LATS1 protein expression in glioma was positively correlated with patient’s overall survival." (PMID 22909338, 2012). "We found that mRNA and protein of LATS1 expression is significantly downregulated in glioma compared with normal control brain tissues." (PMID 22909338, 2012). "Forced expression of LATS1 in glioma U251 cells not only significantly suppressed cell growth, migration and invasion, but retarded cell cycle progression from G2/M to G1 in vitro." (PMID 22909338, 2012). "We measured the expression levels and subcellular localization of LATS1 protein in archived paraffin-embedded normal brain and glioma samples using immunohistochemical staining (Figure 1B1-B5)." (PMID 22909338, 2012). "Using real-time PCR and immunohistochemistry, we detected the mRNA and protein expression of LATS1 in glioma." (PMID 22909338, 2012). "To study its biological functions, we introduced the LATS1 gene into the glioma U251 cell line using pCDF-GFP lentivirus expression vector." (PMID 22909338, 2012). "Further, we applied a gain-of-function approach and to examine the biological processes regulated by LATS1 in glioma cells." (PMID 22909338, 2012). "Further investigation is necessary to determine the exact role LATS1 plays in cell cycle pathway in glioma." (PMID 22909338, 2012). "Next, we used a gain-of-function approach by introducing the LATS1 gene into LATS1-negative U251 glioma cells, to investigate its biological functions." (PMID 22909338, 2012). "In 103 glioma cases with prognosis information, we observed that the level of LATS1 protein expression was significantly correlated with the overall survival of glioma patients." (PMID 22909338, 2012). "Multivariate analysis suggested that the level of LATS1 expression was an independent prognostic indicator (p<0.001) for the survival of patients with glioma." (PMID 22909338, 2012). "Consistent with this presumption, we found that overexpression of LATS1 significantly reduced the expression of CCNA1 by western blot assay in glioma U251 cells." (PMID 22909338, 2012). "Moreover, transwell and wound healing assays suggested that sh-LATS1 reversed the inhibitory impact of sh-S100A16 on glioma migration and invasion in U251 cells." (PMID 37151881, 2023). "In our study, S100A16 was shown to have a promotive impact on glioma proliferation, invasion and metastasis, which might be achieved by knockdown of LATS1." (PMID 37151881, 2023). "This implies that S100A16 may have a potential role in promoting CUL4ADCAF-mediated ubiquitination of LATS1 in glioma." (PMID 37151881, 2023).
glioma (continued). "We have previously validated the LATS1 antibody specificity using LATS1 KD glioma cells." (PMID 37151881, 2023). "FAM66C acts as a tumour suppressor in glioma by targeting miRNA/LATS1 signalling." (PMID 37980632, 2023). "Long non-coding RNA FAM66C regulates glioma growth via the miRNA/LATS1 signaling pathway." (PMID 35935338, 2022). "Moreover, forced expression of LATS1 in U251 glioma cells not only significantly suppressed cell growth, migration, and invasion but also retarded cell cycle progression from G2/M to G1 in vitro." (PMID 33477668, 2021). "Collectively, these data demonstrated that the Hippo-LATS1-YAP axis might play a functional role in PMEPA1a-induced the development of human glioma." (PMID 31605013, 2020). "The result indicated the existence of combination between IKBKE and LATS1/2 in glioma cells." (PMID 29048430, 2017). "YAP1/TAZ-BIRC5 might be abnormally activated due to LATS1/2 down-regulation, which in turn promotes the occurrence and development of gliomas." (PMID 28962630, 2017). "The observations that LATS1 regulates multiple cellular processes such as cell proliferation, cell cycle progression, migration, invasion emphasizes its importance as a therapeutic target for treating glioma." (PMID 22909338, 2012). "LATS1 is a tumor suppressor genes implicated in the pathogenesis of certain types of tumors, but its role is not known in human glioma." (PMID 22909338, 2012). "This suggested LATS1 functions as a tumor suppressor in glioma." (PMID 22909338, 2012). "In a colony formation assay LATS1-overexpressing LATS1-2 and −4 cells formed significantly less colonies than control clone cells (P < 0.001 for both cell types), suggesting the inhibitory effect of LATS1 on anchorage-dependent growth of glioma cells." (PMID 22909338, 2012). "We provided a preliminary molecular mechanism of LATS1-mediated cell growth suppression in glioma." (PMID 22909338, 2012). "Furthermore, we observed expression of LATS1 was markedly decreased in glioma samples compared to normal brain tissues (p<0.001)." (PMID 22909338, 2012). "Our results indicate that the decreased expression of LATS1 appears to favor the development of glioma and might serve a suppressive role in glioma." (PMID 22909338, 2012). "Additionally, our study also revealed a novel function of LATS1 in glioma in suppression of cell migration and invasion." (PMID 22909338, 2012). "Indeed, bioinformatic analysis has predicted that LATS1 might be a potential target for miR-4262, which has been shown to be upregulated in glioma patient samples compared to normal tissue." (PMID 33477668, 2021). "Thus, PMEPA1a suppressed LATS1 protein in glioma cells with an endogenous PMEPA1a expression." (PMID 31605013, 2020). "Furthermore, recent evidence indicates that gliomas express high levels of a splice variant of the prostate transmembrane (TM) protein, androgen induced 1 (PMEPA1) called PMEPA1a, which promotes degradation of the tumor suppressor LATS1 protein." (PMID 31861467, 2019). "This suggested that LATS1 may be involved in G2/M cell cycle pathway in glioma." (PMID 22909338, 2012). "We speculated CCNA1 might be involved in the cell cycle regulation pathway of LATS1 in glioma." (PMID 22909338, 2012). "To further confirm that S100A16 regulates LATS1 protein levels through CUL4A-mediated ubiquitination, we transfected CUL4A siRNA or cDNA into glioma cells pre-treated with MG132." (PMID 37151881, 2023). "LATS1/2 degradation can be mediated by IKBKE (inhibitor of nuclear factor kappa-B kinase subunit epsilon), which was shown to be upregulated in glioma." (PMID 33477668, 2021). "The decreased levels of LATS1 unleash YAP activity and support pro-oncogenic features in glioma cells." (PMID 31861467, 2019). "Meanwhile, data showed that IKBKE did not alter mRNA levels of LATS1/2 in glioma cells supporting the conclusion that this nuclear factor regulates the Hippo pathway through post-translational control of LATS1/2." (PMID 34948224, 2021).
glioma (continued). "Within the Hippo pathway, we here demonstrate, in human gliomas, a functional interaction of a transmembrane protein, prostate transmembrane protein, androgen induced 1 (PMEPA1) with large tumor suppressor kinase 1 (LATS1)." (PMID 31605013, 2020). "Furthermore, reduced LATS1 expression was markedly negatively correlated with WHO grade and KPS (p<0.001 and p<0.001) in glioma patients." (PMID 22909338, 2012). "However, we observed that the expression level of LATS1 was negatively correlated with WHO grade (P<0.016) and KPS in glioma patients." (PMID 22909338, 2012). "Furthermore, the authors demonstrated that IKBKE did not alter mRNA levels of LATS1/2 in glioma cells but was directly bound to LATS1/2, and facilitated its polyubiquitin degradation." (PMID 33477668, 2021). "Meanwhile, our data showed that IKBKE did not alter mRNA levels of LATS1/2 in glioma cells." (PMID 29048430, 2017). "To determine whether LATS1 expression is an independent prognostic factor for glioma, we performed multivariate analysis of the levels of LATS1 protein expression adjusted for LATS1 expression, WHO grade, and KPS of glioma patients." (PMID 22909338, 2012).
lung carcinoma (22 papers, 2015 to 2025). "In line with this concept, PDS5B was associated with the expression of LATS1 in tumor tissues of lung cancer patients." (PMID 34226509, 2021). "Among RASSF family members, RASSF7 functions as an oncogene in lung cancer progression by inhibiting the phosphorylation of mammalian Ste20-like kinase 1, large tumor suppressor kinase 1 and yes-associated protein." (PMID 31768130, 2019). "In addition, mutations and deletions of SAV1 and LATS1/2 are also associated with the proliferation of various tumors, and their predictive role in lung cancer needs further studies." (PMID 38499647, 2024). "In addition, the lung cancer serological indicator NSE susceptibility gene product LATS1 may interfere with apoptosis of tumor cells by regulating the CYFRA21-1 susceptibility gene product YAP." (PMID 34630106, 2021). "On the other hand, deep deletion and promoter methylation in LATS1/2, as well as inactivating mutations in NF2 are frequently reported in malignant mesotheliomas, gynaecologic and lung cancers, in congruence with their tumour-suppressive properties." (PMID 34831354, 2021). "We obtained susceptibility genes corresponding to the four serological indexes associated with lung cancer as follows: NSE, LATS1; CA153, BCAR4; CYFRA21-1, YAP; and CA125, PVT1." (PMID 34630106, 2021). "In the present study, we reported that PDS5B positively regulated the expression of LATS1 in lung cancer cells." (PMID 34226509, 2021). "Remarkably, loss of LATS1/2, resulting in aberrant YAP/TAZ activity, confers erlotinib resistance on HNSCC and lung cancer cells." (PMID 34725466, 2021). "Through literature retrieval and mining technology, we obtained susceptibility genes corresponding to the four serological indexes associated with lung cancer as follows: NSE, LATS1; CA153, BCAR4; CYFRA21-1, YAP; and CA125, PVT1." (PMID 34630106, 2021). "The molecular mechanistic role of TNFAIP8 in the regulation of Hippo signaling by interaction with LATS1 is reported in lung cancer cells." (PMID 30586922, 2018). "In addition, gene fusions involving LATS1 and LATS2 have been found in lung cancer, and low expression level of LATS1 was associated with poor prognosis in patients with NSCLC." (PMID 38499647, 2024). "Notably, the expression of PDS5B was correlated with LATS1 expression levels in tumor specimens in lung cancer patients." (PMID 34226509, 2021). "The methylation of LATS1/LATS2 has been demonstrated in Japanese lung cancer patients." (PMID 26942001, 2016). "In addition, 70% of lung cancer patients exhibited undetectable or lower expression of LATS1." (PMID 34226509, 2021). "It was demonstrated that MST1/2 and LATS1/2 inhibit the expression level of PD-L1, while YAP/TAZ promotes PD-L1 expression in lung cancer cell lines." (PMID 38499647, 2024). "In lung cancer, long noncoding RNA MACC1-AS1 was described to promote stemness through promoting UPF1-mediated destabilization of LATS1/2." (PMID 38339354, 2024). "A recent lung cancer transcriptome meta-analysis showed that several HIPPO pathway component (NF2, LATS1, PTPN14, YAP1, TAZ, TAOK, and FAT1) genes were found to fuse in lung carcinoma, and they were independent prognosis factors for low lung cancer survival." (PMID 36147635, 2022). "Additional gene fusions have also been identified in other vascular and lung cancers involving YAP, TFE3 (transcription factor E3), WWTR1, NF2, LATS1 and LATS2." (PMID 34831354, 2021). "Similar to lung cancer cells TNFAIP8 modulates the Hippo pathway in liver cancer cells by inhibition of YAP phosphorylation and by interaction with LATS1." (PMID 30586922, 2018). "TNFAIP8 interacts with LATS1 and decreases LATS1 phosphorylation, which leads to increased nuclear localization of YAP protein, resulting in increased lung cancer cell proliferation and invasion." (PMID 30586922, 2018).
lung carcinoma (continued). "Notably, overexpression of LATS1 abrogated PDS5B knockdown-induced tumor promotion in NSCLC cells, suggesting that LATS1 is involved in PDS5B-mediated anticancer activity in lung cancer." (PMID 34226509, 2021). "Interestingly, another component of the Hippo pathway, LATS1, has very recently been involved in ATR-mediated response to replication stress in lung cancer cells." (PMID 26393999, 2015).
melanoma (21 papers, 2013 to 2025). A malignant, usually aggressive tumor composed of atypical, neoplastic melanocytes. "LATS1/2-deficient melanomas secreted nucleic-acid-rich extracellular vesicles (EVs) that stimulated the host TLR-MYD88/TRIF-IFN nucleic-acid-sensing pathways, inducing anti-tumor inflammatory reactions." (PMID 38920690, 2024). "In a parallel study, the authors observed the loss of MST2 and LATS1 expression in BRAFi-resistant melanoma cell lines." (PMID 38920690, 2024). "Collectively, our data demonstrate that melanocyte-specific loss of Lats1/2 alone, or in conjunction with oncogenic Braf expression, promotes mouse melanocyte transformation and the formation of mouse melanoma." (PMID 35768444, 2022). "We first interrogated the The Cancer Genome Atlas (TCGA), where we found that co-heterozygous loss of LATS1/2 is observed in ~15% of human melanomas." (PMID 35768444, 2022). "In a parallel study, we have seen that loss of expression of MST2 and LATS1 is common in melanoma cell lines that have acquired resistance to BRAF inhibitors." (PMID 35941108, 2022). "Deletion of LATS1/2 is well established to completely abrogate the Hippo pathway, and co-heterozygous loss of LATS1/2 is observed in ~15% of human melanomas, making deletion of Lats1/2 clinically relevant 2,53." (PMID 35768444, 2022). "The cytometric measurement of intracellular ROS demonstrated that in both melanocytes and melanoma cells in vitro, LATS1 knockdown was associated with a significant increase in ROS levels." (PMID 33803640, 2021). "Activation of YAP/TAZ by loss of the Hippo pathway kinases Lats1 and Lats2 in tumor cells of different murine syngeneic tumor models of melanoma, head and neck carcinoma, and breast cancer enhanced anti-tumor immune responses that lead to cancer cell elimination." (PMID 38538573, 2024). "Similarly, in human melanoma cells, LATS1 has also been implicated in the regulation of ROS, and LATS1 knockdown results in increased oxidative stress." (PMID 38803357, 2024). "Similarly, in the melanoma cell line LATS1 silencing caused an enhanced generation of ROS." (PMID 33803640, 2021). "In A375 melanoma cells, the second mitochondria-derived activator of caspases (SMAC) promotes apoptosis by interacting with LATS1, leading to the degradation of X-linked inhibitor of apoptosis protein (XIAP) in metastatic malignant melanoma." (PMID 41550920, 2025). "Western blot analysis revealed that coculture with iEV-150 significantly reduced the phosphorylation of LATS1 and YAP in melanoma cells, whereas the total protein levels of LATS1 and YAP remained unchanged." (PMID 40860143, 2025). "GST pulldown and coimmunoprecipitation (co-IP) assays revealed that iEV-150 significantly diminished the physical interaction between NF2 and LATS1 in melanoma cells." (PMID 40860143, 2025). "Using three different melanoma cell lines in different syngeneic mouse models, they showed that LATS1/2 deletion abolished the growth of SCC7 tumors and highly reduced tumor growth and the metastasis of B16 and 4T1 cells." (PMID 38920690, 2024). "Our previous study showed that LATS1 silencing reduces the expression of the melanogenesis markers and melanin synthesis in primary melanocytes and melanoma cells." (PMID 38920690, 2024). "Here, we explored the role of LATS1 in the regulation of the canonical proapoptotic machinery and the potential role of this crosstalk in melanoma." (PMID 35941108, 2022). "Here, we confirm the relationship between BRAFV600E, the most common driving mutation of malignant melanoma, and the MST2 pathway and show that it prevents MST2-LATS1 interaction and LATS1-dependent apoptosis." (PMID 35941108, 2022). "We also confirmed that the LATS1-SMAC endogenous interaction is regulated in a RASSF1A-dependent manner in another BRAF-driven melanoma cells SK-Mel239 and in the NRAS-driven melanoma cells SK-Mel2." (PMID 35941108, 2022).